VPS37A (VPS37A subunit of ESCRT-I)
Description:
Component of the ESCRT-I complex, a regulator of vesicular trafficking process. Required for the sorting of endocytic ubiquitinated cargos into multivesicular bodies. May be involved in cell growth and differentiation.
Synonyms: HCRP1; FLJ32642; SPG53; PQBP2
Tractability: Antibody: UniProt places it where antibodies can reach, with medium confidence. PROTAC: ubiquitination databases record sites on it; its protein half-life has been measured.
Gene: Protein-coding gene on chromosome 8 (17,246,896 to 17,302,707, forward strand). Ensembl gene ENSG00000155975.
Subcellular location: Late endosome membrane; Nucleus
Subcellular location (Human Protein Atlas): Acrosome; Centrosome; Flagellar centriole; Vesicles; Cytosol; End piece; Equatorial segment; Mid piece; Nucleoplasm; Perinuclear theca; Principal piece
Pathways (Reactome):
Disease: Budding and maturation of HIV virion; HCMV Late Events; Membrane binding and targetting of GAG proteins
Autophagy: Late endosomal microautophagy
Vesicle-mediated transport: Endosomal Sorting Complex Required For Transport (ESCRT)
Gene Ontology:
Molecular function: protein binding
Biological process: ubiquitin-dependent protein catabolic process via the multivesicular body sorting pathway; macroautophagy; membrane fission; multivesicular body assembly; protein targeting to membrane; protein targeting to vacuole; protein transport to vacuole involved in ubiquitin-dependent protein catabolic process via the multivesicular body sorting pathway; viral budding via host ESCRT complex
Cellular component: ESCRT I complex; nucleoplasm; endosome membrane; late endosome membrane; nucleus
Genetic constraint (gnomAD): Loss-of-function variants: 26 observed, 42.28 expected, observed/expected ratio (o/e) 0.61, 90% interval 0.45 to 0.85. The upper end of that interval is the gene's LOEUF score, 0.85, which puts it in group 3 of 6, group 1 being the genes least tolerant of losing a copy. Missense variants: 560 observed, 429.01 expected, observed/expected ratio (o/e) 1.31, 90% interval 1.22 to 1.4. Synonymous variants: 187 observed, 151.12 expected, observed/expected ratio (o/e) 1.24, 90% interval 1.1 to 1.4.
Gene-disease validity (ClinGen):
ClinGen rates the evidence that VPS37A causes each of these diseases.
complex hereditary spastic paraplegia (autosomal recessive): Limited. A hereditary spastic paraplegia that is part of a larger syndrome.
Homologues: Orthologues: chimpanzee VPS37A (99% identical), macaque VPS37A (98% identical), rabbit VPS37A (94% identical), dog VPS37A (93% identical), guinea pig VPS37A (93% identical), rat Vps37a (91% identical), mouse Vps37a (91% identical), pig VPS37A (90% identical), tropical clawed frog vps37a (65% identical), zebrafish vps37a (62% identical), Drosophila melanogaster Vsp37A (12% identical), Caenorhabditis elegans vps-37 (10% identical). Paralogues in human: VPS37B (13% identical), VPS37C (12% identical), VPS37D (12% identical).
Diseases named in the same sentence as VPS37A in open-access papers:
VPS37A is named in the same sentence as 26 diseases in open-access papers, as found by Europe PMC text mining. Sharing a sentence is not in itself a finding about the gene and the disease. The quoted sentences say what the papers report.
hepatocellular carcinoma (8 papers, 2014 to 2025). A malignant tumor that arises from hepatocytes. "As far as it has been investigated, the picture is less ambiguous for another ESCRT-I subunit, Vps37A: Vps37A mRNA levels were lowered and protein level was significantly reduced in the majority hepatocellular carcinomas analyzed." (PMID 24641493, 2014). "Therefore Vps37A was suggested to be a growth inhibitory protein required to decrease the invasion of hepatocellular carcinoma cells." (PMID 24641493, 2014). "Because VPS37A was originally identified as a cell growth regulatory protein frequently downregulated in hepatocellular carcinoma, it would also be of interest to investigate whether the proposed role of ATG8ylated phagophores contributes to the progression of VPS37A-deficient tumors." (PMID 39976273, 2025). "In HCC, downregulation of VPS37A promoted hepatocellular carcinoma cell migration and invasion by induction of EGFR activation and epithelial-mesenchymal transition." (PMID 29416742, 2018). "It has been reported that VPS37A was downregulated and could be an independent predictor in hepatocellular carcinoma (HCC), non-small cell lung cancer and oropharyngeal cancer." (PMID 29416742, 2018).
breast carcinoma (3 papers, 2015 to 2018). "In breast cancer, VPS37A was downregulated and inhibited breast cancer metastasis through downregulating EGFR phosphorylation." (PMID 29416742, 2018).
ovarian carcinoma (3 papers, 2014 to 2018). A malignant neoplasm originating from the surface ovarian epithelium. "In an inducible human ovarian cancer cell culture model, knockdown of Vps37A was found to cause cytoplasmic pEGFR retention and hyper-activation of downstream AKT and MAPK signaling." (PMID 24641493, 2014). "Beyond that, Vps37A mRNA was significantly down-regulated in ovarian cancer samples." (PMID 24641493, 2014).
colorectal cancer (2 papers, 2018 to 2025). A primary or metastatic malignant neoplasm that affects the colon or rectum. "Although accumulating evidence indicates that VPS37A deficiency occurs in numerous malignancies and exerts tumor-suppressive effects during cancer progression, its functional significance in colorectal cancer (CRC) pathogenesis remains poorly characterized." (PMID 40746890, 2025). "Notably, the pathophysiological contribution of VPS37A to colorectal cancer progression is incompletely characterized and remains to be elucidated." (PMID 40746890, 2025).
hereditary spastic paraplegia (2 papers, 2021 to 2023). Hereditary spastic paraplegias (HSP) comprise a genetically and clinically heterogeneous group of neurodegenerative disorders characterized by progressive spasticity and hyperreflexia of the lower limbs. "The nearby gene VPS37A has also been linked to hereditary spastic paraplegia and belongs to a family of sorting proteins which may be important for tau clearance." (PMID 33757599, 2021).
osteosarcoma (2 papers, 2024). A usually aggressive malignant bone-forming mesenchymal neoplasm, predominantly affecting adolescents and young adults. "The importance of VPS37A UEVL in autophagy was further verified using VPS37A KO U-2 OS human osteosarcoma cells in which the level of HT-GFP processing during autophagy was also found to be comparable to that in LC3 conjugation-defective ATG5 KO cells." (PMID 39607828, 2024).
asthma (1 paper, 2020). "A similar situation was found in a novel lncRNA MSTRG.18506.1 which interacts with three asthma-related genes, i.e., SPDYE6, ATF7IP, VPS37A." (PMID 32948203, 2020).
diabetes (1 paper, 2024). "VPS37A is considered to lead gluconeogenesis in liver cells and diabetes through the cAMP/PKA/p-Creb pathway, but there are no reports showing its role in cancers." (PMID 39329635, 2024).
gastric cancer (1 paper, 2025). A primary or metastatic malignant neoplasm involving the stomach. "In contrast to our screening results, existing data on VPS37A suggest its downregulation as a tumor promoter and an unfavorable prognostic indicator in breast and gastric cancers, indicating a potential MPM-specific role." (PMID 40180891, 2025).
Nephropathy (1 paper, 2022). A nonspecific term referring to disease or damage of the kidneys. "VPS37A is a very important protein in the cellular autophagy pathway, but its role in the pathogenesis of nephropathy is not well characterized." (PMID 36465646, 2022).
rectal adenocarcinomas (1 paper, 2025). "While ubiquitously expressed in normal tissues, VPS37A showed significant downregulation in numerous malignancies, with particularly pronounced suppression in colorectal (COAD) and rectal adenocarcinomas (READ)." (PMID 40746890, 2025).
cancer (9 papers, 2013 to 2025). A tumor composed of atypical neoplastic, often pleomorphic cells that invade other tissues. "VPS37A is frequently lost or downregulated across a wide variety of malignancies, which is associated with cancer progression and poor prognosis." (PMID 40746890, 2025). "As expected, AURKA ablation significantly inhibited proliferation in all cell lines, whereas CDK2 and VPS37A knockout selectively suppressed growth in cancer cells." (PMID 40180891, 2025). "Moreover, by comparing the 13 survival-related gene lists, seven genes (SLK, API5, BTBD2, PTAR1, VPS37A, EIF2B1, and ZRANB1) were found to be associated with prognosis in a variety of cancers." (PMID 32300588, 2020). "This approach unveiled cancer cell-selective hits such as BUB1, CDK2, and VPS37A." (PMID 40180891, 2025). "Our focus also extended to CDK2 and VPS37A genes, both of unknown biological significance in MPM, whose depletion by CRISPR should selectively affect cancer cells." (PMID 40180891, 2025). "Importantly, a number of studies have shown changes in expression of ESCRT components in human cancer cells, including changes in expression of ESCRT-I components Tsg101 and Vps37A and ESCRT-III components Chmp1A and CHMP3." (PMID 23418496, 2013).
tumor (7 papers, 2014 to 2025). "Collectively, our data establish VPS37A as a key tumor suppressor in CRC, where its loss promotes oncogenesis through dysregulated cell cycle progression and uncontrolled proliferation." (PMID 40746890, 2025). "These multi-omics findings establish VPS37A as a consistently downregulated tumor suppressor in CRC, suggesting its loss may represent an early carcinogenic event." (PMID 40746890, 2025). "Furthermore, both the integrative multi-omics analysis and immunohistochemical validation using our CRC patient cohort (Cohort 2) consistently confirmed that low VPS37A expression is significantly associated with advanced tumor stages and reduced overall survival in CRC." (PMID 40746890, 2025). "Having established VPS37A’s tumor-suppressive role in CRC, we investigated its potential involvement in cell death regulation." (PMID 40746890, 2025). "Here, we report that VPS37A, a core subunit of the ESCRT-I complex, functions as a tumor suppressor in CRC, where its loss promotes oncogenic progression through dysregulation of cell cycle control and proliferation in vitro and in vivo." (PMID 40746890, 2025). "VPS37A overexpression suppressed tumor growth (p < 0.0001) and reduced final tumor weight (p < 0.0001) compared to controls." (PMID 40746890, 2025). "This metabolic stress-specific suppression aligns with VPS37A’s proposed tumor-suppressive function, suggesting that VPS37A mediates context-dependent tumor suppression in CRC by differentially regulating cell death pathways under metabolic stress." (PMID 40746890, 2025). "GSEA revealed suppression of G2/M CHECKPOINT (NES = −2.16, p < 0.05) and E2F TARGETS (NES = −2.02, p < 0.05), while KEGG analysis showed inhibition of CELL CYCLE pathways (NES = −1.77, p < 0.05), aligning with VPS37A’s tumor-suppressive role." (PMID 40746890, 2025). "Gene expression analysis of the GSE42977 dataset revealed significant upregulation of AURKA, CDK2, and VPS37A in MPM tumor tissues compared to normal mesothelial and lung tissues." (PMID 40180891, 2025). "Similarly, VPS37A, an ESCRT component linked to autophagy and membrane trafficking, has been implicated in tumor progression." (PMID 40180891, 2025). "This paradoxical activation of oncogenic signaling contrasts with VPS37A’s established tumor-suppressive role, suggesting that VPS37A may exert context-dependent tumor-suppressive functions in CRC through mechanisms extending beyond canonical cell cycle regulation." (PMID 40746890, 2025). "Notably, the expression patterns of both the upregulated and downregulated gene sets closely resembled those of transgenic and chemically induced mouse models of HCC67 in the Molecular Signatures Database (MSigDB), indicating a tumor suppressor function for VPS37A-mediated autophagosome closure." (PMID 39607828, 2024). "To decode the tumor-suppressive regulatory network of VPS37A, we analyzed transcriptional profiles of VPS37A-overexpressing (SW620/VPS37A) and control cells (SW620/Ctrl) using RNA sequencing." (PMID 40746890, 2025). "Overall, Hrs (ESCRT-0) and Tsg101 (ESCRT-I) seem to be mostly up- and Vps37A (ESCRT-I), Chmp1A and Vps4B mostly down-regulated in tumor samples." (PMID 24641493, 2014). "As for Tsg101, there is some evidence for a potential tumor suppressor role of another ESCRT-I subunit, Vps37A." (PMID 24641493, 2014).
VPS37A also shares sentences with these, for which no sentence is quoted: prostate carcinoma (3 papers); non-small cell lung carcinoma (2); oropharyngeal cancer (2); renal cell carcinoma (2); basal cell carcinoma (1); colon cancer (1); Cushing syndrome (1); infection (1); neurodegenerative disease (1); non-alcoholic fatty liver disease (1); non-alcoholic steatohepatitis (1); small cell lung carcinoma (1); viral infection (1).